ADAM17 (ADAM metallopeptidase domain 17)
Diseases named in the same sentence as ADAM17 in open-access papers (continued):
Sharing a sentence is not in itself a finding about the gene and the disease.
tumor (continued). "Compared to ADAM17, ADAM10 expression was significantly lower in both tumor regions, with higher levels in TC compared to IC within MIBC (p = 0.004) and CIS (p = 0.007)." (PMID 33672843, 2021). "The mRNA expression of ADAM17 and ADAM10 was much higher in TNBC as compared with non-tumor tissues." (PMID 34169001, 2021). "ADAM17 can serve as a prognostic biomarker for advanced CRC, contributing to the development of new therapies focused on reducing tumor metastasis." (PMID 34502094, 2021). "ADAM17 was a key mediator of chemoresistance in HCT116 cells, and its promoting effect on tumor growth was also discovered in previous research." (PMID 33005106, 2020). "More important, there were elevated expression levels of ADAM10, ADAM17, and ADAM19 in tumor tissues as they became more malignant in terms of pathological grading." (PMID 33043016, 2020). "Consistently, we show that PP2A‐B56 binding to ADAM17 reduces EGFR Tyr1068 autophosphorylation and suppresses in vivo tumor growth." (PMID 32400009, 2020). "Furthermore, the growth of ADAM17‐deficient A549 tumor xenografts in NSG mice was significantly impaired compared to ADAM17‐expressing control A549 xenografts, as demonstrated by ~4‐fold and ~5‐fold reductions in final (day 21) tumor volumes and weights, respectively." (PMID 30833304, 2019). "The limited number of studies investigating ADAM17 in NSCLC has suggested that elevated ADAM17 expression correlates with numerous clinicopathological characteristics (e.g., tumor grade) and poor survival." (PMID 30833304, 2019). "MEDI3622, another antibody for ADAM17, was produced to bind to a unique hairpin loop in the ADAM17 structure, and it was useful in an EGFR-dependent tumor model." (PMID 30460232, 2018). "They showed reduced tumor growth-rate and decreased shedding of the ADAM17 substrates TNFR1-α, AREG, and TGF-α in a xenograft model, upon ADAM17 inhibition." (PMID 29662625, 2018). "In the present work, we identified ZLDI-8, a novel inhibitor of ADAM-17 and found that pre-treatment of ZLDI-8 enhanced the anti-tumor effect of Sorafenib and traditional chemotherapeutic agents via in vitro or in vivo models." (PMID 29970890, 2018). "CD163 has been used as a marker to evaluate macrophage infiltration, and its ectodomain (also called soluble CD163, sCD163) can be cleaved by ADAM17 (ADAM metallopeptidase domain 17) gene, which is closely related with tumor metastasis." (PMID 29152078, 2017). "A disintegrin and metalloproteinase-17 (ADAM17, also named as tumor necrosis factor-alpha-converting enzyme, TACE) is expressed in most tissues and is upregulated during inflammation, tumor growth, and angiogenesis." (PMID 27110571, 2016). "Patients with tumours characterized by low levels of PTEN and high levels of ADAM17 (PTENlowADAM17high) had also a worse clinical outcome compared with other patient groups." (PMID 27941799, 2016). "In sum, our findings demonstrate that p110 CUX1 enhanced the levels of ADAM17, which in turn leads to NOTCH signalling activation validating our observation in vivo in different tumour models." (PMID 27941799, 2016). "ADAM17 and EGFR increase the expression of HIF-α, and HIF-α then activates VEGF and VEGFR to stimulate tumor angiogenesis." (PMID 25544346, 2015). "miR-122 is a powerful tumor suppressor, by inhibiting angiogenesis, tumorigenesis and HCC intrahepatic metastasis, partially by targeting ADAM metallopeptidase domain 17 (ADAM17)." (PMID 25272224, 2014). "ADAM17 expression, likewise other ADAM family members, is up-regulated in many types of cancers, correlating with tumor progression and aggressiveness." (PMID 24495306, 2014). "We tested a series of new ADAM-17 inhibitor compounds (TMI-1, TMI-2, TMI-005) for their potential ability to block tumor cell growth." (PMID 23028451, 2012).
tumor (continued). "The potential importance of other immune system-related ADAM17 substrates as IL-6R or MIC-A/B, the ligands of NKG2D receptors, in murine tumor development is questionable because of species specificity." (PMID 23251384, 2012). "IGROV1-Luc tumour cells in vitro secreted TNF-α, TNFR1-α, TGF-α, AREG, HB-EGF and IL-6Rα, all known substrates for the shedding activity of ADAM17, into the culture medium even when unstimulated." (PMID 22792380, 2012). "Inhibition of ADAM17 by D1(A12) antibody was expected to inhibit TNF-α secretion and thereby inhibit growth of IGROV1-Luc tumours in vivo." (PMID 22792380, 2012). "Regulating the activities of ADAM10 and ADAM17 to inhibit the shedding of MICA/B on cancer cells can significantly promote the degranulation of peripheral, liver, and tumor-infiltrating NK cells and the production of IFN-γ, enhancing the anti-tumor activity of NK cells." (PMID 40563539, 2025). "Compared to control groups with either no T cell transfer (Ctrl) or T cells transduced with an empty vector (Mock), CAR-T cells (CAR) exhibited potent anti-tumor activity, whereas CAR-T cells engineered to knockdown ADAM17 (CAR ADAM17 shRNA) had remarkably enhanced tumor eradication efficacy." (PMID 38918390, 2024). "Therefore, the tumor weight was reduced in ADAM17 KO mice, accompanied by an increased percentage and cell number of CD8+ tumor-infiltrating lymphocytes (TILs)." (PMID 38918390, 2024). "CD8+ T cells from WT mice were transduced with either anti-hB7-H3 CAR or anti-hB7-H3 CAR expressing an shRNA against Adam17, and adoptively transferred into tumor-bearing mice with MC38 expressing hB7-H3, without additional IL-2/sumIL-2 treatment." (PMID 38918390, 2024). "Furthermore, our investigation revealed a notable upregulation of several matrix metalloproteinases (MMPs) in tumor-infiltrating macrophages, including MMP9, MMP12, MMP19, ADAM8, ADAM9, and ADAM17." (PMID 38254761, 2024). "These in vivo experiments confirmed that suppressing ADAM17 expression increases VE-cadherin expression at the tumor invasion front, thereby mitigating the upregulation of CRC hematogenous metastasis and pre-metastatic niche formation otherwise induced by ADAM17." (PMID 38413999, 2024). "The presented results indicate the significant correlation between the CXCL12, CXCR4, CXCL8/CXCR2, M-CSF, MMP-2, MMP-9 ADAM17, ADAMTS-6, and CLDN7 levels and tumor stage, as well as the clinicopathological parameters of OC, such as the presence of lymph node and/or distant metastases." (PMID 38673838, 2024). "Similarly, si-ADAM17 positive and negative validation in HPMECs demonstrated that EMT-HCT116-derived exosomal ADAM17 promotes HPMEC permeability and tumor cell adhesion by targeting the VE-cadherin-mediated vascular endothelial barrier." (PMID 38413999, 2024). "Similarly, the tumor size and weight were decreased while the percentage and cell number of OT-1+ CD8+ TILs were increased in mice that received ADAM17 KO CD8+ T cells." (PMID 38918390, 2024). "When proteolytically processed by the cell membrane proteases TACE/ADAM17, AREG is secreted, behaves as an autocrine or paracrine factor, and may thus also modify the tumor microenvironment." (PMID 38727313, 2024). "As the non-canonical pathway is considered oncogenic, ADAM17 mediates EphA2 pS897-dependent tumor growth and (IR-induced) cell migration." (PMID 36998455, 2023). "Both ADAM10 and ADAM17 expression correlate with tumor size, metastasis and TNM stage, being a negative prognostic factor." (PMID 37185715, 2023). "In some tumor types expression of ADAM10 and ADAM17 was increased compared to normal tissue." (PMID 37732732, 2023). "For example, in invasive BC the expression of ADAM17 is significantly increased in high-grade tumors independent of tumor size, lymph node involvement, and ER status." (PMID 36901756, 2023).
tumor (continued). "ADAM17 is involved in the processing of the extracellular matrix and the release of various growth factors and cytokines that contribute to the remodeling of the TME and facilitate tumor cell dissemination." (PMID 36998455, 2023). "The expression of ADAM17 was assessed using IHC in 79 pairs of HCC and adjacent non-tumour tissues." (PMID 38069391, 2023). "Regarding the pro-angiogenic and lymphangiogenic roles of NOX1 and ADAM17 in CRC, we hypothesized that sMCAM could act as a lymphangiogenic growth factor and promote tumor lymphangiogenesis." (PMID 38137406, 2023). "In addition, ADAM17 through TNF/TNFR1 signaling is crucial for tumor cell–induced endothelial cell necroptosis and vascular permeability, which facilitates tumor cell extravasation and metastasis." (PMID 36720499, 2023). "It has been reported that ADAM17 may enhance the malignant potential of CRC cells via increasing their motility and the expression of proangiogenic factors, promoting tumour progression and metastasis." (PMID 35565436, 2022). "In addition, CCL2 secreted by tumor cells and macrophages promotes PKCβ activation by binding to endothelial CCR2, which further leads to ADAM17 activation." (PMID 36466812, 2022). "In addition, miR-145 downregulates ADAM17 expression by binding to the 3’-UTR of ADAM17, which leads to activation of the ADAM17-EGFR-Akt-C/EBP-β feedback loop and induction of tumor invasion." (PMID 36466812, 2022). "ADAM10 and ADAM17 were recently shown to produce different cleavage products of PD-L1 that are shed from the surface of tumor cells, leading to apoptosis of CD8+ T cells and inhibition of anti-tumor immunity." (PMID 36591235, 2022). "It has been reported that the absence of ADAM17 is sufficient to inhibit IL-6 trans-signaling-mediated tumor formation in the ApcMin/+ model." (PMID 36270986, 2022). "In the tumor, the protein concentration of ADAM17 was also lower in women, but not statistically significant." (PMID 36286024, 2022). "Furthermore, HDAC6 enhances ADAM17 activity, increases the release of sIL-6R and promotes the M2 polarization of macrophages in the TME, thus allowing immune escape and promoting tumor development." (PMID 36270986, 2022). "In addition, iRhom2, as a key binding protein for ADAM17, further promotes KRAS-induced tumor cell growth by modulating the release of ERBB ligands." (PMID 36466812, 2022). "In this way, ADAM17-dependent shedding constitutes a regulatory pathway, which could potentially be targeted to shift the TME from cancer promoting to tumor inhibiting." (PMID 35998057, 2022). "By using phage-display technology, Rios-Doria and colleagues developed another ADAM17 inhibitory antibody, MEDI3622, that blocked ADAM17 activity, and consequently, release of TNF in LPS-stimulated mice and tumor progression in a head and neck patient-derived xenograft model." (PMID 33579029, 2021). "For PDAC, the expression of ADAM17 (p = 0.008, IHC-score 3.43 vs. 1.73), CD44 (p = 0.012, IHC-score 3.64 vs. 2.27), Notch1 (p = 0.012, IHC-score 2.21 vs. 0.64), and Notch4 (p = 0.008, IHC-score 2.86 vs. 0.91) was significantly higher in the tumor tissue." (PMID 33498866, 2021). "Importantly, tumors including GBM often secrete NKG2D ligands, for example, through cleavage by ADAM10 and ADAM17 molecules, which often results in decreased surface expression of NKG2D on NK cells and reduced NKG2D-mediated anti-tumor response." (PMID 34926577, 2021). "Specifically, ADAM17 is known to have a major role in activating most ligands of EGFR, such as amphiregulin, heparin-binding epidermal growth factor and epigen, representing a crucial pathway for tumor progression." (PMID 34224305, 2021). "Additionally, the ADAM17 inhibitor ZLDI-I, by preventing 5-FU-mediated upregulation of Notch1-4, improved the anti-tumor activity of 5-FU and reversed EMT, acting in a synergic or additive way in different concentrations." (PMID 34680255, 2021).
tumor (continued). "We further observed an overall negative association between NME4 and tumor invasion markers like genes encoding matrix-degrading proteases (MMP7, ADAM17) and actin cytoskeleton remodelers (ROCK1, ROCK2, LIMK2, CFL2, MYO5A)." (PMID 34674701, 2021). "Moreover, for ADAM17 substrates such as Nectin-4 and HB-EGF, it was shown that increased levels contribute to tumor proliferation." (PMID 34771725, 2021). "However, inhibition of TACE/ADAM-17 reduces mTNFα shedding on IFN-DC membranes and enhances the cytotoxic DC activity against TNFα/TNF-R1-sensitive tumor cells." (PMID 32326230, 2020). "Along these lines, strategies targeting tumor ADAMs may synergize with ADCC, although it is still debated whether ADAM17-mediated CD16 cleavage could induce NK cell detachment from the target cell and eventually favor tumor escape." (PMID 32272610, 2020). "ADAM17, also known as TACE (tumor necrosis factor α [TNF-α]-converting-enzyme), has been reported to be a Notch receptor molecular scissor, which leads to tumorigenesis and tumor progression." (PMID 32405532, 2020). "Unlike ADAM9, other ADAM family genes ADAM10 and ADAM17 neither differed in their expression levels between HCC tumor tissues and adjacent normal liver tissues, nor showed significant correlation with survival analysis." (PMID 32245188, 2020). "Moreover, modulating the interaction between ADAM17 and PP2A‐B56 had profound effects on in vivo tumor growth." (PMID 32400009, 2020). "Using the Cancer Genome Atlas database, we found that higher expression of ADAM9 in tumor tissues was associated with poorer survival of HCC patients (log-rank p = 0.00039), while ADAM10 and ADAM17 exhibited no such association." (PMID 32245188, 2020). "Our results indicated that CD82 could directly interact with ADAM17 and influence its protease activity, which refreshed our current knowledge about the mechanism of CD82 as a tumor metastasis suppressor." (PMID 33204367, 2020). "These biomarkers include ADAM17, MMP2, MMP9, and MMP11, survivin and CK19, vimentin, CXCR4, ING5, and Stanniocalcin2; in all of these examples, these molecules are overexpressed in tumoral GC tissues." (PMID 31249523, 2019). "Moreover, a high level of ADAM-17 was detected in HCC cell lines compared with L-02, a non-tumor haptic cell line." (PMID 31611551, 2019). "The increased pADAM17 activity in LAC patients was not a consequence of elevated ADAM17 expression, since ADAM17 mRNA and protein (pro/mature) levels were unchanged in tumor versus non‐tumor tissues in LAC patient cohorts (Fig EV4B and C)." (PMID 30833304, 2019). "The increased presence of ADAM17 is of critical relevance as it does not only shed AREG but was found to be the essential protease that releases five additional EGFR-ligands and a variety of factors which are crucial in tumor development and chemo resistance." (PMID 29662625, 2018). "However, the cleavage of amphiregulin is mediated by different metalloproteinases such as ADAM17, which is regulated by O2 tension and HIF2, and the latter is related to iron influx in tumor cells." (PMID 29682205, 2018). "Once the tumors were established, tumor growth rates were not altered suggesting that once established, leukocyte-specific ADAM17 is dispensable for tumor growth (data not shown)." (PMID 27738494, 2016). "MDSC-induced L-selectin loss occurs through a contact-dependent, post-transcriptional mechanism that is independent of the major L-selectin sheddase, ADAM17, but results in significant elevation of circulating L-selectin in tumor-bearing mice." (PMID 27929373, 2016). "ADAM17 has been shown to promote migration of tumor cells, non-transformed keratinocytes, and vascular endothelial cells." (PMID 26176220, 2015). "The results showed that ADAM17 expression was not correlated with gender, age, tumor size, location or necrosis." (PMID 25364437, 2014).
tumor (continued). "Variation in sALCAM among studies may have multiple causes: sALCAM must pass through the barrier of tumor tissue and vascular endothelial cells to be flushed into the blood stream, and sequential sectioning has failed to establish a direct relationship between ADAM17/TACE and ALCAM." (PMID 23940674, 2013). "Upon phorbol ester and ionophore stimulation, we observed a mild increase in ADAM17 surface expression for some but not all tumor cell lines and for primary and activated T cells." (PMID 24130797, 2013). "ADAM-metalloproteinases, particularly ADAM17 and 10, are repeatedly found in microvesicles derived from tumor cells; however, neither their function nor mechanism of uploading from parental cells is understood." (PMID 26082068, 2012). "Thus, D1(A12) has anti-ADAM17 activity in vivo, inhibits shedding of EGFR ligands and has potential for use in EGF ligand-dependent tumours." (PMID 22792380, 2012). "At the same time, serum levels of TNF, IFNγ, and MCP-1 were lower in mice bearing ADAM17-silenced tumors than mock-transfected ones, which is not surprising as serum levels of the cytokines usually correlate with the tumor size." (PMID 23251384, 2012). "An increased level of TNF protein in ADAM17-silenced tumors may partially result from a diminished activity of ADAM17, which prevents TNF release from tumor cells." (PMID 23251384, 2012). "In addition, we found that tumor related genes, such as PTGS2, ADAM17 and FOS, are highly expressed in the ITA infection group, suggesting that ITA may lead to more severe N. farcinica infections." (PMID 40723822, 2025). "To confirm whether TMI-5-based ADAM17 inhibition may have a direct in vivo anti-angiogenic effect, independent of the presence of a tumor, we tested the ability of TMI-1 and TMI-5 to inhibit endothelial cell sprouting in the ex vivo aortic ring model." (PMID 38137406, 2023). "Since ADAM17 is the subsequent step following FGFR2 activation in migration and proliferation of EC cells, targeting ADAM17 function in FGFR2-mutant cells may have a beneficial effect in tumor suppression." (PMID 37759450, 2023). "The ADAM17 expressed on the surface of tumor cells has been reported to bind to the activating receptors (CD16 and NKG2D) of NK cells and rupture them; at the same time, it acts as a proteolytic enzyme by participating in the shedding of B7-H6, which is highly expressed in tumor cells." (PMID 35372056, 2022). "In addition, the increased ectodomain cleavage of other ADAM17 substrates (GPIBα and HPP1) may be required for immune platelet clearance and tumor suppression." (PMID 36466812, 2022). "To determine whether receptor cleavage is involved in the production of cell-derived sTNFR1 and sTNFR2 by TNBC cells, we used the broad spectrum metalloproteinase inhibitor marimastat and the ADAM17 inhibitor TAPI-0 which did not affect tumor cell growth." (PMID 35884574, 2022). "In addition, we found that the expressions of FOXM1, ADAM17, NOTCH1 and N-cadherin were decreased in SPAG5-downregulated tumor tissues, while E-cadherin expression was increased, highlighting the role of SPAG5 in downregulation of the expression of FOXM1, ADAM17 and NOTCH1, and inhibiting EMT." (PMID 35138218, 2022). "Immunohistochemical stains of RB patient tumor sections revealed a moderate (13 out of 20, 65%) to high expression (4 out of 20, 20%) of ADAM17 in most of the tumors analyzed, while three out of 20 (15%) tumors displayed negative for ADAM17." (PMID 36293469, 2022). "In agreement with the mixed normal and tumor datasets, PBMC displayed positive correlations between ACE2/TMPRSS2, TMPRSS2/FURIN, ACE2/TFRC, FURIN/TFRC, TMPRSS2/CTSL, FURIN/CTSL, TMPRSS2/MYC, and FURIN/AKT1 and a negative association between ACE2/ADAM17." (PMID 33796097, 2021).